EGFR (epidermal growth factor receptor)
Diseases named in the same sentence as EGFR in open-access papers (continued):
Sharing a sentence is not in itself a finding about the gene and the disease.
metastatic colorectal cancer (continued). "We examined acquired mutations in chemoresistant lesions and blood obtained from four patients with RAS wild-type metastatic colorectal cancer who underwent treatment with anti-epidermal growth factor receptor antibodies." (PMID 34840814, 2021). "cetuximab is an antibody to epidermal growth factor receptor (EGFR) that is used for treatment of metastatic colorectal cancer, metastatic non-small cell lung cancer, and head and neck cancer." (PMID 33449240, 2021). "Treatment with anti-epidermal growth factor receptor (EGFR) monoclonal antibodies (mAbs)—cetuximab and panitumumab—produced clinical benefits in a subset of patients with metastatic colorectal cancer (mCRC)." (PMID 33562755, 2021). "Anti-EGFR-related skin toxicity has been described as a predictive biomarker of response in patients with RAS wild-type (WT) metastatic colorectal cancer (mCRC)." (PMID 34830870, 2021). "In the last decade, molecular evaluation in patients with metastatic colorectal cancer (mCRC) has been widely used to assess primary resistance to anti-epidermal growth factor receptor (EGFR) based therapy." (PMID 34660299, 2021). "Cetuximab and panitumumab are monoclonal antibodies (mAbs) against epidermal growth factor receptor (EGFR) that are effective agents for metastatic colorectal cancer (mCRC)." (PMID 34663410, 2021). "Monoclonal antibody treatments that act on EGFR, including Cmab and Pmab, are recommended for Ras wild-type-metastatic colorectal cancer as candidates for first-line to third-line therapy." (PMID 33489709, 2021). "Panitumumab is a human monoclonal antibody targeting the epidermal growth factor receptor for the treatment of wild-type RAS metastatic colorectal cancer (mCRC)." (PMID 34213592, 2021). "Previous clinical trials have demonstrated the potential efficacy of rechallenge with anti- epidermal growth factor receptor (EGFR) monoclonal antibodies (mAbs) for patients with RAS/BRAF V600E wild-type metastatic colorectal cancer (mCRC)." (PMID 34098908, 2021). "Background and Purpose: RAS mutations limit the effectiveness of anti-epidermal growth factor receptor (EGFR) monoclonal antibodies in combination with chemotherapy for metastatic colorectal cancer (mCRC) patients." (PMID 32308771, 2020). "Metastatic colorectal cancers (mCRCs) assigned to the transit-amplifying (TA) CRCAssigner subtype are more sensitive to anti–epidermal growth factor receptor (EGFR) therapy." (PMID 33015526, 2020). "KRAS and NRAS mutations are predictors of primary resistance to the EGFR-antibodies (EGFR-Abs) cetuximab and panitumumab in metastatic colorectal cancer (mCRC)." (PMID 33322618, 2020). "The treatment of metastatic colorectal cancer (mCRC) was deeply changed by the introduction of anti-EGFR “targeted therapy” (TT)." (PMID 32164324, 2020). "Cetuximab and panitumumab, which are directed against the epidermal growth factor receptor (EGFR), are the most common monoclonal antibody used in metastatic colorectal cancer (mCRC) to prolong survival." (PMID 31720832, 2020). "Lately, honokiol is reported to be a promising natural compound in overcoming acquired resistance to cetuximab, a monoclonal antibody against EGFR used for treatment of head and neck squamous cell carcinoma and metastatic colorectal cancer." (PMID 32210117, 2020). "Epidermal growth factor receptor antibodies (EGFR-Abs) confer a survival benefit in patients with RAS wild-type metastatic colorectal cancer (mCRC), but resistance invariably occurs." (PMID 33322618, 2020). "The HERACLES trial was a multicenter open-label phase II trial that enrolled patients with wild-type KRAS exon 2, HER2 overexpressing metastatic colorectal cancer refractive to chemotherapy, and anti-EGFR therapy resistance." (PMID 31720832, 2020).
metastatic colorectal cancer (continued). "Ongoing clinical trials are recently investigating the efficacy of second-line EGFR inhibitors in initially RAS mutant metastatic colorectal cancer patients who convert to RAS wild-type in plasma, as assessed by circulating tumor DNA (ctDNA) analysis." (PMID 33291569, 2020). "Recently, honokiol is reported to be a promising natural compound in overcoming acquired resistance to cetuximab, a monoclonal antibody against EGFR used for treatment of head and neck squamous cell carcinoma and metastatic colorectal cancer." (PMID 32210117, 2020). "The discovery of mutant KRAS as a predictor of resistance to epidermal growth factor receptor (EGFR) monoclonal antibodies led to a major change in the treatment of metastatic colorectal cancer." (PMID 33183271, 2020). "In patients with metastatic colorectal cancer (CRC) the clinical implementation of targeted therapy strategies against the epidermal growth factor receptor (EGFR) has become a well-established oncological therapy option." (PMID 33002027, 2020). "Mutations in KRAS, NRAS, and BRAF (RAS/BRAF) genes are the main predictive biomarkers for the response to anti-EGFR monoclonal antibodies (MAbs) targeted therapy in metastatic colorectal cancer (mCRC)." (PMID 32628708, 2020). "The now clinically-used anti-epidermal growth factor receptor (EGFR) monoclonal antibodies have demonstrated significant efficacy only in patients with metastatic colorectal cancer (mCRC), with wild-type Kirsten rat sarcoma viral oncogene homolog (KRAS)." (PMID 32839411, 2020). "Cetuximab, a monoclonal antibody therapy targeting the epidermal growth factor receptor (EGFR), is given in combination with chemotherapy as the standard of care for a subset of metastatic colorectal cancer patients." (PMID 32481658, 2020). "In this study we used error corrected ctDNA-sequencing to identify genetic drivers of resistance in metastatic colorectal cancer (mCRC) patients that had become resistant to combined chemotherapy and EGFR-antibody treatment." (PMID 33322618, 2020). "Anti-epidermal growth factor receptor (EGFR) monoclonal antibody was the therapy commonly used for metastatic colorectal cancer patients with wild-type RAS (KRAS/NRAS) genes." (PMID 33213472, 2020). "Metastatic colorectal cancer (mCRC) remains challenging because of the emergence of resistance mechanisms to anti-epidermal growth factor receptor (EGFR) therapeutics, so more effective strategies to improve the patients’ outcome are needed." (PMID 32650388, 2020). "A growing body of data has shown that the location of the primary tumor can be both prognostic and predictive of response to EGFR inhibitors in metastatic colorectal cancer." (PMID 33299406, 2020). "Anti-epidermal growth factor receptor (EGFR) antibody is widely used for the treatment of patients with metastatic colorectal cancer." (PMID 31637554, 2019). "Epidermal growth factor receptor is a potential target for metastatic colorectal cancer with safety, tolerability, and pharmacokinetics being explored in multiple clinical trials." (PMID 30478887, 2019). "Patients with metastatic colorectal cancer can benefit from anti-EGFR therapy, such as cetuximab and panitumumab." (PMID 31711486, 2019). "Targeting the epidermal growth factor receptor (EGFR) either alone or in combination with chemotherapy in patients with RAS wild type metastatic colorectal cancer (mCRC) has revolutionized the treatment of CRC, but with less results than initially envisaged." (PMID 31370270, 2019). "Monoclonal antibodies which inhibit signaling downstream the epidermal growth factor receptor (EGFR) have become one of the mainstays of targeted therapy in metastatic colorectal cancer (mCRC)." (PMID 32039027, 2019). "Targeting the epidermal growth factor receptor (EGFR) either alone or in combination with chemotherapy is an effective treatment for patients with RAS wild-type metastatic colorectal cancer (mCRC)." (PMID 31164152, 2019).
metastatic colorectal cancer (continued). "Epidermal growth factor receptor (EGFR)-targeted monoclonal antibodies, including cetuximab and panitumumab, are used to treat metastatic colorectal cancer (mCRC)." (PMID 31771279, 2019). "In RAS and KRAS wild-type metastatic colorectal cancer patients, miR-31-3p was used as a molecular marker to predict the response of anti-EGFR therapy." (PMID 31776419, 2019). "This case report reminds clinicians that LOC can be induced without severe hypomagnesemia or QTc prolongation, during anti-EGFR antibody treatment for metastatic colorectal cancer even while under carefully monitored magnesium supplementation." (PMID 31637554, 2019). "Monoclonal antibodies targeting epidermal growth factor receptor (EGFR) or vascular endothelial growth factor (VEGF) have demonstrated efficacy in combination with chemotherapy as second line for metastatic colorectal cancer (mCRC)." (PMID 31443300, 2019). "A relevant role for NGS is the prediction of response to anti-EGFR agents in metastatic colorectal cancer (mCRC), where multiple exons from KRAS, NRAS, and BRAF must be sequenced simultaneously." (PMID 31036005, 2019). "Anti-epidermal growth factor receptor (EGFR) antibodies (anti-EGFR-Ab) are effective in a subgroup of patients (pts) with metastatic colorectal cancer (CRC)." (PMID 31287991, 2019). "This less time-consuming and less laborious method can enable precision medicine to be offered to patients with metastatic colorectal cancers, such as anti-EGFR therapy." (PMID 31711486, 2019). "Monoclonal antibodies targeting epidermal growth factor receptor (EGFR) or vascular endothelial growth factor (VEGF) have demonstrated efficacy with chemotherapy (CT) as second line treatment for metastatic colorectal cancer (mCRC)." (PMID 31443300, 2019). "Anti-EGFR therapy is used to treat metastatic colorectal cancer (CRC) patients, for which initial response rates of 10–20% have been achieved." (PMID 30858928, 2019). "In the management of patients with RAS wild-type metastatic colorectal cancer (mCRC), anti-epidermal growth factor receptor (EGFR) therapies have demonstrated a clinical benefit, with longer survival." (PMID 31253124, 2019). "Molecular mechanisms driving acquired resistance to anti-EGFR therapies in metastatic colorectal cancer (mCRC) are complex but generally involve the activation of the downstream RAS-RAF-MEK-MAPK pathway." (PMID 31842958, 2019). "Currently, there are two FDA approved anti-EGFR mAbs for cancer therapies in the USA, Cetuximab and Panitumumab for metastatic colorectal cancer, and Cetuximab for locoregional head and neck cancer." (PMID 31508364, 2019). "The combination of the classic chemotherapy with antibodies against EGFR or VEGFR (to inhibit angiogenesis) has contributed to increase the overall survival in metastatic colorectal cancer (mCRC)." (PMID 31370270, 2019). "Different types of treatment are available for patients with advanced metastatic colorectal cancer, including targeted biological agents, such as cetuximab, a monoclonal antibody that targets EGFR." (PMID 31545548, 2019). "In metastatic colorectal cancer, RAS and BRAF mutations cause resistance to anti‐EGFR therapies, such as cetuximab." (PMID 31350822, 2019). "Further to small-molecule EGFR inhibitors, anti-EGFR monoclonal antibodies cetuximab and panitumumab are approved for the treatment of metastatic colorectal cancer." (PMID 30146241, 2018). "Molecular genetic studies targeting metastatic colorectal cancer (mCRC) tumors have identified mutations in KRAS and NRAS that predict a lack of therapeutic response to epidermal growth factor receptor (EGFR) inhibitors." (PMID 30019318, 2018). "An emerging biological therapeutic agent is represented by panitumumab, a fully human anti-EGFR monoclonal antibody therapeutic designed to treat metastatic colorectal cancer." (PMID 30282914, 2018).
metastatic colorectal cancer (continued). "In the past decade, the development of novel biologic agents including therapies directed against vascular endothelial growth factor and epidermal growth factor receptor has further altered the landscape of metastatic colorectal cancer treatment." (PMID 30519549, 2018). "International guidelines made RAS (KRAS and NRAS) status a prerequisite for the use of anti-EGFR agents for metastatic colorectal cancer (CRC) patients." (PMID 29755687, 2018). "On the other hand, blocking the activation of EGFR, an antibody that selectively binds EGFR-by Cetuximab, has shown to improve the response rate of 5-Fu in patients with metastatic colorectal cancer who initially failed 5-FU-based therapy." (PMID 29932172, 2018). "Cetuximab (CTX) is a monoclonal antibody targeting the epidermal growth factor receptor (EGFR), commonly used to treat patients with metastatic colorectal cancer (mCRC)." (PMID 30261609, 2018). "Few data are available regarding the treatment of metastatic colorectal cancer elderly patients with anti-EGFR agents in combination with chemotherapy." (PMID 29370781, 2018). "In patients with metastatic colorectal cancer, treatment using EGFR-directed antibodies such as cetuximab or panitumumab is recommended." (PMID 30186857, 2018). "Genotyping of oncogenic RAS mutations is routinely undertaken as it is an important biomarker used to predict drug resistance to epidermal growth factor receptor (EGFR)-targeted monoclonal antibodies in patients with metastatic colorectal cancer (mCRC)." (PMID 29849949, 2018). "In the evolving molecular landscape of metastatic colorectal cancer, optimizing available tools to select patients to receive anti-epidermal growth factor receptor (anti-EGFR) monoclonal antibodies is a modern challenge of colorectal oncologists." (PMID 30081606, 2018). "Cetuximab, an anti-EGFR monoclonal antibody, is used in combination with chemotherapy in clinic to enhance the outcome in metastatic colorectal cancer (mCRC) patients with only ~ 20% response rate." (PMID 29703253, 2018). "Skin toxicity (ST) is a frequent adverse effect (AE) in anti-epidermal growth factor receptor (EGFR)-targeted treatment of metastatic colorectal cancer (mCRC) resulting in decreased quality of life and problems in clinical management." (PMID 30100989, 2018). "EGFR-targeted therapy is a key treatment approach in patients with RAS wildtype metastatic colorectal cancers (CRC)." (PMID 28199979, 2017). "Outcomes for metastatic colorectal cancer (mCRC) patients have been improved by treatment with anti-epidermal growth factor receptor (anti-EGFR) antibodies, particularly when combined with predictive biomarkers to select patients lacking RAS mutations." (PMID 28368335, 2017). "American Society of Clinical Oncology (ASCO) guidelines recommend that all patients with metastatic colorectal cancer (mCRC) receive KRAS testing to guide anti-EGFR monoclonal antibody treatment." (PMID 29202108, 2017). "We found no clinical benefit of restricting combination therapy with bevacizumab for metastatic colorectal cancer patients with EGFR-wild type tumors." (PMID 28068936, 2017). "Earlier studies from our laboratory show that longer TL has potential to be positive predictive biomarker of clinical outcome to anti-epidermal growth factor receptor (EGFR) monoclonal antibody therapy in patients with KRAS WT metastatic colorectal cancer." (PMID 28740573, 2017). "Erbitux has been granted full approval by the U.S. Food and Drug Administration for the first-line treatment of patients with EGFR-expressing metastatic colorectal cancer." (PMID 28031526, 2017). "IgG antibodies specific for the extracellular domain of EGFR were detected in the sera of patients with metastatic colorectal cancer before receiving cetuximab." (PMID 29354119, 2017).
metastatic colorectal cancer (continued). "The potential interest of miR-31-3p expression as a predictive biomarker of the response to anti-EGFR therapy in metastatic colorectal cancer has been previously reported in several papers." (PMID 29212194, 2017). "Targeting the epidermal growth factor receptor (EGFR) either alone or in combination with chemotherapy is effective for patients with RAS wild type metastatic colorectal cancer (mCRC)." (PMID 28002810, 2017). "KRAS exon 2 mutations were the first validated predictive biomarker for primary resistance to anti-epidermal growth factor receptor (EGFR) monoclonal antibodies (cetuximab and panitumumab) in patients with metastatic colorectal cancer (mCRC)." (PMID 28972961, 2017). "Future large and independent studies are necessary for confirming the correlation between low EZH2 expression and unfavorable prognosis in patients with metastatic colorectal cancer who have received anti-EGFR therapy." (PMID 28147317, 2017). "Monoclonal antibodies targeting the epidermal growth factor receptor (EGFR), cetuximab and panitumumab, are a mainstay of metastatic colorectal cancer (mCRC) treatment." (PMID 28507280, 2017). "K-Ras mutation status is a strong predictive marker of resistance to EGFR-targeted therapy in patients with metastatic colorectal cancer." (PMID 27926503, 2017). "High EGR1 expression correlates with resistance to anti-EGFR treatment in vitro and poor outcome in metastatic colorectal cancer patients treated with cetuximab." (PMID 29246166, 2017). "For example, cetuximab, a specific EGFR inhibitor, has been used for the treatment of metastatic colorectal cancer, metastatic non-small cell lung cancer and head and neck cancer." (PMID 28541302, 2017). "To date, of the anti-EGFR monoclonal antibodies (mAbs), only cetuximab and panitumumab have been approved for the treatment of patients with metastatic colorectal cancer (mCRC) with RAS wild-type status." (PMID 28032593, 2017). "Over the past few years, KRAS mutation testing has become compulsory as a prerequisite for the treatment of patients with metastatic colorectal cancer (mCRC), with anti-EGFR monoclonal antibody (mAb) therapies such as cetuximab or panitumumab." (PMID 27681846, 2017). "They analyzed serum levels of different growth factors in patients with metastatic colorectal cancer who were treated with an anti-EGFR antibody and also found a significant inverse correlation between serum levels of HGF and OS." (PMID 28456787, 2017). "These preclinical findings provide a compelling rationale for evaluating the combination of anti‐EGFR antibodies with TAS‐102 against metastatic colorectal cancer." (PMID 28486761, 2017). "Subsequent studies showed that mutated KRAS acted as an in vivo oncogenic driver, as indicated by studies of anti-EGFR therapy for metastatic colorectal cancers." (PMID 27102293, 2016). "Cetuximab and panitumumab are two mAbs that are approved for the treatment of EGFR-expressing metastatic colorectal cancer with KRAS wild-type." (PMID 27655662, 2016). "Barely 10-20% of patients with metastatic colorectal cancer (mCRC) receive a clinical benefit from the use of anti-EGFR monoclonal antibodies (mAbs)." (PMID 27102434, 2016). "In metastatic colorectal cancer, we previously investigated the clinical role of serum ligands in predicting the prognosis of anti-EGFR antibody treatment." (PMID 26716644, 2016). "Mutation analysis of KRAS is needed before starting treatment with monoclonal anti-EGFR antibodies in patients with metastatic colorectal cancer (mCRC)." (PMID 26812617, 2016). "Epidermal Growth Factor Receptor (EGFR) targeted therapies using monoclonal antibodies (mAbs) such as cetuximab and panitumumab are widely used for the treatment of metastatic colorectal cancer (mCRC)." (PMID 27314237, 2016). "Nevertheless, only 10-20% of patients with metastatic colorectal cancer (mCRC) benefit from anti-EGFR mAbs therapy." (PMID 27102434, 2016).